EPHA3 (EPH receptor A3)
Diseases named in the same sentence as EPHA3 in open-access papers (continued):
Sharing a sentence is not in itself a finding about the gene and the disease.
glioma (continued). "EphA2 and EphA3 were highly expressed in the mesenchymal subtype glioma according to The Cancer Genome Atlas database." (PMID 35448036, 2022). "Ephrin type-A receptor 3 (EPHA3) is a membrane-associated receptor that is overexpressed in the stroma and vasculature of gliomas." (PMID 31779126, 2019). "Since EphA2, EphA3 and ephrin-B2 were described to regulate tumor-propagating cell self-renewal, luciferase-transfected glioma stem cells (TPC8 cell line) were injected into mouse brains." (PMID 29849945, 2018). "In vivo imaging and distribution studies on the glioma-bearing rats showed that anti-EPHA3-modified NPs exhibited high fluorescence intensity in the brain and effectively accumulated to glioma tissues, indicating the targeting effect of anti-EPHA3." (PMID 30176744, 2018). "EphA3 is significantly elevated in recurrent disease, is most highly expressed on glioma stem cells (GSCs), and has a functional role in maintaining self-renewal and tumourigenesis." (PMID 30562956, 2018). "We next examined EphA3 in relation to macrophages because these cells highly infiltrate gliomas, contributing to total tumor mass." (PMID 27494882, 2016). "Furthermore, in vivo anti-glioma experiments with C6 glioma-bearing rats demonstrated that TBE-loaded anti-EPHA3-decorated NPs induced markedly higher tumor cell apoptosis and prolonged the median survival time compared to controls." (PMID 39911305, 2025). "Anti-EPHA3 demonstrated significant accumulation within the glioma, indicating its specificity." (PMID 39911305, 2025). "Notably, expression was highest in the U251CL and U87 lines, while relatively lower levels were observed in U118, A172, SU-DIPG36GL, SU-DIPG4, SU-DIPG13, SU-DIPG33, underscoring the potential for EphA3-targeted CAR therapies in diverse glioma contexts." (PMID 39111833, 2024). "In conclusion, while the data strongly support the clinical exploration of EphA3 CAR T cells in glioma treatment, it is paramount to consider the intertumor and intratumor heterogeneity that may influence therapeutic outcomes." (PMID 39111833, 2024). "• Overexpressionof EphA3 is reported on the tumor-initiatingcell population in glioma." (PMID 35786935, 2022). "Similarly, anti-EphA3 bound nanoparticles loaded with the DNA alkylation agent temozolomide showed specific tumor targeting and potent anti-tumor effects in a rat glioma model." (PMID 34926242, 2021). "Importantly, EPHA3 is highly expressed on the tumor-initiating cell population in glioma, which potentially maintains tumor cells in a less differentiated state by modulating mitogen-activated protein kinase signaling." (PMID 32211330, 2020). "Ephrin type-A receptor 3 (EPHA3), a membrane-associated receptor, which is particularly overexpressed in stroma and vasculature in gliomas but not in normal tissues, can be used as a functional target for the treatment of GBM." (PMID 30176744, 2018). "Glioma-bearing rats treated with anti-EPHA3-modified NPs resulted in significantly higher tumor cell apoptosis (p < .01) than that observed with other formulations and prolonged the median survival time of glioma-bearing rats to 26 days, which was 1.37-fold longer than that of PLGA NPs." (PMID 30176744, 2018). "In addition, the CAR T cell responses to adult glioma (with high EphA3 expression) were more effective than against a glioma target expressing lower antigen levels, highlighting the importance of target antigen density in patient selection in clinical trial design." (PMID 39111833, 2024). "The results from a rat glioma C6 cell cytotoxicity assay and subsequent experiments on specific cellular uptake demonstrated enhanced GBM targeting due to anti-EPHA3 modification." (PMID 40076445, 2025). "EphA3 was shown to be overexpressed in 40% of GBM patients’ samples, with high expression in glioma stem cells, allowing tumors to remain in an undifferentiated and tumorigenic state." (PMID 39111833, 2024).
glioma (continued). "In this study, we referred to the advantages of TBE-NPs in brain delivery and constructed TMZ16e-based anti-EphA3-modified NPs, aiming to deliver TMZ16e to GBM efficiently and overcome the challenges of drug-resistant glioma treatment." (PMID 36059989, 2022). "The anti-EphA3-modified TMZ@GNPs (anti-EphA3-TMZ@GNPs) were synthesized for chemical and auxiliary plasma photothermal therapy (PPTT) in order to solve the issue of glioma resistance to TMZ, and to enhance GBM therapeutic benefits." (PMID 36015322, 2022). "Notably, the highest expression levels were detected in U251CL and U87 glioma lines, while it was lower in others such as SU-DIPG36GL suggesting a possible correlation between EphA3 expression levels and the efficacy of targeted CAR T cell therapies." (PMID 39111833, 2024). "EphA3 is a membrane-associated receptor that can be used as a functional target for the treatment of GBM since it is overexpressed in stroma and vasculature in gliomas but not in normal tissues." (PMID 40076445, 2025). "Furthermore, the formation of a memory T-cell population following EphA3 CAR T cell treatment suggests the potential for long-term immunity against glioma recurrence, a critical aspect often lacking in conventional treatments." (PMID 39111833, 2024). "Therefore, the EphA3 antibody (anti-EphA3) as a non-fucosylated IgG1j (human f-allotype) monoclonal antibody with low toxicity can further enhance glioma targeting via its specific interactions with the EphA3 receptor." (PMID 36059989, 2022). "In this study, anti-ephrin type-A receptor 3 (EphA3) modified TMZ16e loaded nanoparticles (NPs) were prepared for targeted GBM therapy via intranasal administration to deliver TMZ16e to the brain, treat drug-resistant glioma effectively, and reduce peripheral toxicity." (PMID 36059989, 2022). "A representative example shows that αDG and EphA3 are expressed predominantly in regions, where mesenchymal tumour elements are present and expression is low or absent on the more differentiated GFAP+ glial tumour element." (PMID 31463571, 2019).
lung carcinoma (21 papers, 2011 to 2025). "EPHA3 has been revealed to be the most frequently mutated Eph receptor gene in lung cancer with abnormal expression." (PMID 27101199, 2016). "We report here a thorough study to address the physiological role of the putative lung cancer tumor suppressor EPH receptor A3 (EPHA3), a gene that is frequently mutated in human lung adenocarcinomas." (PMID 25713296, 2015). "We also found that a lung cancer mutation identified in the second fibronectin type III repeat of EphA3 enhances the cis association of the receptor with ephrin-A3." (PMID 24348920, 2013). "We found that the EphA3 G518L lung cancer mutation strengthens the cis association of EphA3 with coexpressed ephrin-A3." (PMID 24348920, 2013). "We also found that an EphA3 mutation identified in lung cancer enhances cis interaction with ephrin-A3." (PMID 24348920, 2013). "We infected the NCI-H226 and A549 lung cancer cell lines with lentiviruses encoding EphA3 and ZsGreen from a bicistronic transcript or only ZsGreen as a control." (PMID 24348920, 2013). "EphA3 mutations are particularly frequent in lung cancer and can act as “drivers” in lung cancer." (PMID 38811954, 2024). "It was further shown that the mutation and abnormal expression level of EPHA3 were correlated with lung cancer and gastric cancer, respectively, which confirmed that EPHA3 could be considered as a target in cancer therapy." (PMID 36765579, 2023). "EPHA3 is a receptor tyrosine kinase that is frequently mutated in lung cancer." (PMID 25861239, 2015). "Furthermore, EphA3 is among the most highly mutated genes in lung cancer and it is also frequently mutated in other cancers." (PMID 25993310, 2015). "EPHA3 mutations are implicated in lung cancer and are distributed throughout the domains of EPHA3." (PMID 24817905, 2014). "To examine whether EphA3 can also be regulated by cis interaction with ephrin-B2, we infected A549 lung cancer cells expressing EphA3 with lentiviruses encoding EGFP-ephrin-B2 or only EGFP as a control." (PMID 24348920, 2013). "EphA3 is frequently overexpressed in various types of tumors, such as melanoma, lung carcinoma, and sarcoma, where it functions as a tumor-specific antigen." (PMID 38811954, 2024). "Re-expression of wild-type EPHA3 in human lung cancer lines increased apoptosis by suppression of AKT activation in vitro and inhibited the growth of tumor xenografts." (PMID 27101199, 2016). "Our studies utilizing Epha3-null mice fail to validate a putative tumor suppressor function for EPHA3 in human lung cancer." (PMID 25713296, 2015). "Similar to previous findings in murine Kras lung cancer studies, all EphA3 genotype cohorts displayed distinct types of progressive lesions, including epithelial hyperplasia, adenomas and ADCs." (PMID 25713296, 2015). "We indeed found that ephrin-A3 overexpressed in lung cancer cells can inhibit EphA2 and EphA3 activation by ephrins in trans while overexpression of ephrin-B2 can inhibit activation of EphA3 and EphB4." (PMID 24348920, 2013). "While the role of specific EPH receptor mutations has been functionally studied in certain tumour types, like EPHA3 in lung cancer, the role of EPHB1 somatic mutations had not been studied to date." (PMID 38102712, 2023). "Two EphA3 mutations related to lung cancer refer to EphA3 lacking partially or almost completely the Sam domain." (PMID 36142306, 2022). "Moreover, EPHA3 gene copy numbers and/or expression levels were decreased in tumors from large cohorts of patients with lung cancer." (PMID 27101199, 2016). "Thus, EphA3-null mice fail to validate a putative tumor suppressor function for EPHA3 in human lung cancer, perhaps owing to functional redundancy between murine EphA receptors expressed in adult lungs." (PMID 25713296, 2015). "For example, the EphA3 mutation in lung tissue promoted lung cancer, indicating non-mutated EphA3 inhibited cancer." (PMID 25978371, 2015).
lung carcinoma (continued). "Next-generation sequencing of lung cancer patient tumors has identified numerous putative new cancer drivers, including EPH (also defined as erythropoietin-producing hepatocellular) receptor A3 (EPHA3), which is mutated in 6–16% of lung ADC samples." (PMID 25713296, 2015). "Thus, in lung cancer cells, coexpressed ephrin-A3 can inhibit EphA2 and EphA3 activation by ephrin ligands." (PMID 24348920, 2013). "Current evidence indicated that EPHA3 was closely associated with immune cell infiltration and the efficacy of immunotherapy in tumors such as lung cancer and bladder cancer, suggesting that EPHA3 may play a role in regulating immunogenicity and the immune microenvironment." (PMID 40406118, 2025). "Inhibition of tumour growth in vivo by two NSCLC cell lines expressing wild-type EphA3, but not EphA3 mutants, shows that the EphA3 can act as a tumour suppressor in lung cancer." (PMID 36830852, 2023). "EPHA3 and EPHA4 reduced the development of metastasis and could possibly be useful biomarkers for prognosis in lung cancer." (PMID 35008410, 2022). "However, we did not observe enrichment of EphA3 and ephrin-A3 in regions of cell-cell contact in A549 lung cancer cells coexpressing these proteins (not shown)." (PMID 24348920, 2013). "Thus, coexpressed ephrin-A3 in lung cancer cells inhibits ephrin binding to EphA3 in trans without reducing EphA3 expression or surface localization." (PMID 24348920, 2013).
melanoma (19 papers, 2010 to 2025). A malignant, usually aggressive tumor composed of atypical, neoplastic melanocytes. "Among the identified markers associated with melanoma, EPHA3, encoding the EPH receptor, has been implicated in cell repulsion, adhesion, and motility." (PMID 38233802, 2024). "The recruitment of Crk to ephrin-stimulated EphA3 in melanoma and 293T cells also caused a brief rise in activated Rho, which resulted in cell contraction and membrane blebbing." (PMID 36830852, 2023). "To confirm the previous findings that the EphA3 is associated with melanoma malignancy, we measured its expression in melanoma tissues and cells." (PMID 36578556, 2022). "Mutations in EPHA3 have been detected in melanoma, and several ephrin-derived peptide antigens (from EPHA2, EPHA3 and EPHB6) can be recognized by cancer-specific cytotoxic T-cells." (PMID 21494657, 2011). "In melanoma progression, somatic and germline mutations of EphA3 have been detected." (PMID 36578556, 2022). "EPHA3 (ephrin type-A receptor 3) was found to be significantly mutated in 28 melanoma cases." (PMID 25393105, 2014). "EphA3 is the first receptor with dual significance, being recognized as a tumor antigen in lymphoblastic leukemia cells and, independently, in melanoma cells from a patient with an EphA3-reactive T cell immunological response." (PMID 38952552, 2024). "EphA3 has also been identified as highly expressed in leukemia, melanoma, and bladder, colorectal, esophageal, gastric, and prostate cancers, and particularly high expression in liver cancer." (PMID 39111833, 2024). "Previous studies have also demonstrated that the activation of EPHA3 is observed in certain melanoma samples, leading to tumor metastasis through the modulation of Rho-dependent cytoskeleton reorganization and cell retraction." (PMID 38233802, 2024). "To analyse the effects of EphA3 knockdown in the TME of tumours in which the tumour cells also express EphA3, we used subcutaneous tumours of B16F10 mouse melanoma cells, which have robust EphA3 expression." (PMID 37760615, 2023). "Independently, a CD4+ T-cell clone derived from a melanoma patient with disease regression was found to recognise an EphA3 epitope and to induce a preferential immune response against melanoma cells." (PMID 36830852, 2023). "Herein, our aim is to explore how EphA3 impacts melanoma in vitro and in vivo and identify the interaction of miR-3666 and EphA3 on melanoma cells." (PMID 36578556, 2022). "Indolium 1 has a novel mechanism of action against melanoma, in that it results in induction of the tumor-suppressor EPHA3." (PMID 35624662, 2022). "Having verified the function of EphA3 in vitro, we next examined if EphA3 is necessary for melanoma malignancy in vivo." (PMID 36578556, 2022). "Collectively, EphA3 targeted by miR-3666 contributes to melanoma malignancy via activating ERK1/2 and p38 MAPK pathways." (PMID 36578556, 2022). "Our data showed that EphA3 was highly expressed in melanoma tissues and cells, and EphA3 silence mitigated the tumorigenic potential of melanoma in vitro and in vivo." (PMID 36578556, 2022). "In our present work, we found that EphA3 silence inhibited melanoma cells’ proliferation and migration by inactivating ERK1/2 and p38 MAPK signaling pathways." (PMID 36578556, 2022). "Based on above results, upon EphA3 silence, evident impairments in cell proliferation were detected in both melanoma cells." (PMID 36578556, 2022). "One of the most upregulated genes in terms of chromatin accessibility is EPHA3, which has relevance in melanoma biology." (PMID 35624662, 2022). "In summary, our results showed that miR-3666 targeting EphA3 downregulated EphA3 expression and thereby suppressed the melanoma cell proliferation and migration through disruption of ERK1/2 and p38 MAPK signaling pathways." (PMID 36578556, 2022). "Although EPH receptor A3 (EphA3) is deregulated in melanoma, its detailed role remained uncharacterized." (PMID 36578556, 2022).
melanoma (continued). "In a word, EphA3 promoted the malignant phenotypes of melanoma through driving ERK1/2 and p38 MAPK signaling pathways." (PMID 36578556, 2022). "Cell counting kit-8, scratch wound, and in vivo assays proved that EphA3 silence inhibited the melanoma cell proliferation and migration and retarded tumor growth in vivo." (PMID 36578556, 2022). "Using real time quantitative PCR analysis and western blotting, EphA3 was identified to be upregulated in melanoma tissues and cells, while miR-3666 showed an opposite expression trend." (PMID 36578556, 2022). "As its interaction with EphA3, miR-3666 mimic abrogated the increased proliferation and migration of melanoma cells driven by EphA3 overexpression through ERK1/2 and p38 MAPK signaling pathways." (PMID 36578556, 2022). "Second, the activation of wild-type EPHA3 causes downregulation of AKT, which has previously been implicated in melanoma progression." (PMID 35624662, 2022). "In conclusion, miR-3666 downregulated EphA3 expression and retarded melanoma malignancy via inactivating ERK1/2 and p38 MAPK pathways." (PMID 36578556, 2022). "It was independently identified on tumor cells from a melanoma patient by virtue of an EphA3-reactive T cell immune response." (PMID 32397088, 2020). "We analyzed the expression of three receptor tyrosine-kinases (RTKs) that are involved in tumor cell growth and are overexpressed in murine melanoma cells, e.g. Kit, Met and EphA3." (PMID 28079159, 2017). "Hypoxic (1–2% O2) culture of EphA3+eSCs, as well as cells with low/undetectable EphA3 (TECs) or with measurable EphA3 expression (A09 melanoma), significantly increased EphA3 mRNA levels in all cases." (PMID 25420155, 2014). "Significantly mutated gene analysis using 13 WGS cases and 15 additional paired extension cases identified known melanoma genes such as BRAF, NRAS, and CDKN2A, as well as a novel gene EPHA3, previously implicated in other cancer types." (PMID 25393105, 2014). "For instance, EphA3/ephrinA5 signaling induces growth cone collapse in retinal ganglion cells and cell rounding, blebbing, and detachment in EphA3-expressing human kidney epithelial cells and melanoma cell lines." (PMID 20224755, 2010). "Furthermore, the identification of EPHA3 as a significant player in melanoma progression suggests its potential as a therapeutic target." (PMID 38233802, 2024). "Mechanically, miR-3666 could abrogate the pro-proliferation and pro-migration effect of EphA3 overexpression on melanoma cell growth by inactivating ERK1/2 and p38 MAPK signaling pathways." (PMID 36578556, 2022). "Together with literature review and bioinformatics analysis, we hypothesize that miR-3666 is downregulated in melanoma and inhibits melanoma development by targeting EphA3." (PMID 36578556, 2022). "And EphA3 overexpression boosted melanoma cell proliferation and migration in vitro." (PMID 36578556, 2022). "The tumor suppression of EphA3 silence in melanoma in vitro was further validated by in vivo." (PMID 36578556, 2022). "Our findings suggest that miR-3666/EphA3 axis might be an effective target for melanoma intervention." (PMID 36578556, 2022). "Third, EPHA3 has been shown to be a tumor neoantigen in melanoma." (PMID 35624662, 2022). "Therefore, miR-3666 downregulates EphA3 expression and suppresses melanoma malignancy via suppressing ERK1/2 and p38 MAPK pathways." (PMID 36578556, 2022). "Therefore, the activation of ERK1/2 and p38 MAPK signaling pathways plays an important role in EphA3-driven melanoma cell proliferation and migration." (PMID 36578556, 2022). "Similarly, in the three melanoma cells (A375, A875, and A2058), the high expression of EphA3 was confirmed compared to HaCAT cells." (PMID 36578556, 2022).